NLRP3 (NLR family pyrin domain containing 3)
Diseases named in the same sentence as NLRP3 in open-access papers (continued):
Sharing a sentence is not in itself a finding about the gene and the disease.
head and neck squamous cell carcinoma (continued). "In human head and neck squamous cell carcinoma (HNSCC), NLRP3, ASC, CASP1, IL1B and IL18 gene expression is increased as compared to oral mucosa." (PMID 33261061, 2020). "Head and neck squamous cell carcinoma (HNSCC) is closely related to chronic inflammation, and elevated NLRP3 inflammasome expression in HNSCC tissue has been shown and the degree of expression has been associated with disease prognosis." (PMID 30447690, 2018). "Moreover, our previous study showed that CD38 deletion upregulates TLR4 expression, and also, there is a paper reporting that CD38 can induce inflammasome-mediated activation of caspase-1 by activating NLRP3 in head and neck squamous cell carcinoma (HNSCC)." (PMID 33860064, 2021). "While, Inflammasome-mediated cancer recently attracted great interest, and NLRP3 inflammasome plays an important role in the development of a variety of solid tumors, including head and neck squamous cell carcinoma (HNSCC) and oral squamous cell carcinoma (OSCC)." (PMID 31312615, 2019). "Extensive studies have been conducted on P2XR and/or NLRP3 inflammasome in colon cancer, melanoma, prostate cancer, and lung cancer, but only a few studies has been done in the field of Head and Neck Squamous Cell Carcinoma (HNSCC)." (PMID 28430665, 2017). "More recent studies have shown systemic pharmacologic inhibition of NLRP3 to increase effector CD8+ T cells and suppress both CD4+FoxP3+ regulatory T cells and CD11b+Ly6G+Ly6Clo PMN-MDSCs in a transgenic Tgfbr1/Pten 2ccKO model of head and neck squamous cell carcinoma." (PMID 34638239, 2021). "In Head and neck squamous cell carcinoma (HNSCC) Laryngeal squamous cell carcinoma ( LSCC), and squamous cell carcinoma tissues, for instance, NLRP3 is overexpressed in comparison to normal tissues; this overexpression is frequently associated with a poor prognosis and worse pathology." (PMID 37715239, 2023).
lung adenocarcinoma (28 papers, 2016 to 2025). A carcinoma that arises from the lung and is characterized by the presence of malignant glandular epithelial cells. "Activation of NLRP3 inflammasome has been reported associated with the pathogenesis of RA, cardiovascular diseases, and lung adenocarcinoma." (PMID 35153741, 2021). "Interestingly, one study has identified NLRP3 exonic mutations associated with FLIP-mediated anti-apoptosis in ~16% of lung adenocarcinomas." (PMID 34638239, 2021). "Notably, recent studies in lung adenocarcinoma have revealed select gain-of-function mutations in NLRP3 to drive FLIP-dependent inhibition of apoptosis, thus promoting tumorigenesis." (PMID 34638239, 2021). "Interestingly, NLRP3 activation mutations are present in 16% of lung adenocarcinomas and are significantly enriched for NF-κB activity." (PMID 26657290, 2016). "The NLRP3 inflammasome enhances lung adenocarcinoma cell A549 proliferation by activating the IL-1β/ERK/CREB and IL-18/AKT/CREK signaling pathways." (PMID 40026444, 2025). "We further analyzed the influence of core genes on lung adenocarcinoma prognosis, and survival analysis revealed a significant association between CASP1, NLRP3, NLRP1, and AIM2 and overall survival in patients with lung adenocarcinoma." (PMID 40026444, 2025). "CASP1, NLRP3, AIM2, and NLRP1 are core pyroptotic genes in lung adenocarcinoma, significantly associated with immune cell infiltration, diagnosis, and prognosis in this condition." (PMID 40026444, 2025). "The results showed that CASP1, NLRP3, AIM2, and NLRP1 exhibited excellent diagnostic efficacy, suggesting their potential utility as diagnostic biomarkers for lung adenocarcinoma." (PMID 40026444, 2025). "Our focus was constructing a diagnostic and prognostic model for lung adenocarcinoma based on the core genes—CASP1, NLRP3, AIM2, and NLRP1." (PMID 40026444, 2025). "Herein, we examined the signaling networks and influence of melatonin on TAM-regulated tumor angiogenesis and lymphangiogenesis via inhibition of the NLRP3 axis in the lung adenocarcinoma cell TME." (PMID 39230586, 2024). "In this current paper, we sought to combine XRT with an NLRP3 agonist to further boost the priming process and generate systemic antitumor responses in murine-implanted lung adenocarcinoma models." (PMID 37289257, 2023). "Canonical activation of the NLRP3 inflammasome enhances the proliferation and metastasis of lung adenocarcinoma cells." (PMID 36694200, 2023). "NLRP3 activation is the downstream event of TNF-α that induces epithelial–mesenchymal transition (EMT) in lung adenocarcinoma cell line A549." (PMID 36932407, 2023). "In lung adenocarcinoma, higher NLRP3 level in patient specimens is correlated with latter stage and lymph node metastasis." (PMID 36932407, 2023). "Studies have indicated that NLRP3 inflammasome activation enhances the proliferation and metastasis of the lung adenocarcinoma cell line A549, which are mediated by AKT, ERK1/2, and CREB, and upregulation of SNAIL42." (PMID 37337018, 2023). "This suggests that ANGPTL4 regulates gefitinib resistance in lung adenocarcinoma cells through the NLRP3/ASC/Caspase8 pathway." (PMID 36467503, 2022). "Collectively, ANGPTL4 inhibits lung adenocarcinoma cell pyroptosis and apoptosis by regulating the NLRP3\ASC\Caspase 8 pathway both in vivo and in vitro." (PMID 36467503, 2022). "Another study using human lung adenocarcinoma A549 cells demonstrated that NLRP3 inflammasome activation can enhance the proliferation and migration of A549 cells." (PMID 30696442, 2019). "Evaluation using ROC curves for core genes indicated that CASP1, NLRP3, AIM2, and NLRP1 demonstrate excellent diagnostic potential for lung adenocarcinoma and may serve as diagnostic markers for the disease." (PMID 40026444, 2025).
lung adenocarcinoma (continued). "Interestingly, somatic mutations in NLRP3 together with 10 other genes including KEAP1, KRAS, and STK11 were reported to define a molecular signature associated with a subtype of NSCLC, the lung adenocarcinoma (LUAD)." (PMID 36746533, 2023). "Conversely, activation of the NLRP3 inflammasome promotes the proliferation and migration of lung adenocarcinoma A549 cells, which is related to the ability of the NLRP3 inflammasome to mediate the release of IL-18 and IL-1β through caspase-1-dependent or caspase-1-independent pathways." (PMID 35246158, 2022). "Some previous studies suggested that NLRP3 downregulation inhibited EMT and metastasis in in vitro and in vivo experiments, and the targeting of NLRP3 may be a promising strategy for the treatment of lung adenocarcinoma." (PMID 31312615, 2019). "The synonymous mutation (c.1299C>A) in NLRP3 was archived in the COSMIC database from a lung adenocarcinoma tumor sample (TCGA-50-5941-01), and the nonsynonymous mutations of neither NLRP3 nor PBX1 were archived in dbSNP, 1,000 Genomes Project, ExAC database, and COSMIC." (PMID 36091765, 2022). "This further confirms the pyroptosis core gene CASP1, NLRP3, AIM2, and NLRP1 expression levels in lung adenocarcinoma and their connection to immune infiltration." (PMID 40026444, 2025). "For instance, NSCLC shows overexpressed AIM2, while lung adenocarcinoma and small cell lung cancer (SCLC) show upregulated NLRP3." (PMID 36932407, 2023). "ANGPTL4 inhibited pyroptosis and apoptosis by regulating the NLRP3/ASC/Caspase 8 pathway, leading to resistance to gefitinib in lung adenocarcinoma." (PMID 36467503, 2022). "Given this evidence, a melatonin-mediated targeting of the NLRP3 axis may be a promising approach to preventing TAM-regulated angiogenesis and lymphangiogenesis in lung adenocarcinoma." (PMID 39230586, 2024). "Therefore, in this study, we paired intratumoral injection of an NLRP3 agonist with XRT to stimulate the immune system in both wild type (344SQ-P) and anti-PD1 resistant (344SQ-R) murine-implanted lung adenocarcinoma models." (PMID 36824846, 2023). "For example, the inflammasome NLRP3 is widespread in CRC, lung adenocarcinoma, etc.." (PMID 34966747, 2021). "Harnessing the positive aspects of NLRP3 agonism, we hereby demonstrated the boosted priming effect and improved systemic antitumor responses with the combined treatment of XRT and NLRP3 agonist, in both wild type and anti-PD1 resistant murine-implanted lung adenocarcinoma models." (PMID 37289257, 2023). "Because of no clear conclusion confirming the specific role in lung adenocarcinoma, TLR4 attracts our attention, which enables to stimulate NLRP3 inflammasomes via enhancing the activation of nuclear factor-κB (NF-κB), releasing more pro-inflammatory cytokines like IL-1β and IL-18." (PMID 37553698, 2023). "In summary, the combination of XRT + NLPR3 agonist enhanced control of implanted lung adenocarcinoma primary as well as secondary tumors in a radiological dose-dependent manner, in which 12Gyx3 fractions of stereotactic XRT was better than 5Gyx3, while 1Gyx2 did not improve the NLRP3 effect." (PMID 37289257, 2023). "We found that the combination of XRT + NLPR3 agonist enhanced the control of implanted lung adenocarcinoma primary as well as secondary tumors in a radiological dose-dependent manner, in which 12Gyx3 fractions of stereotactic XRT was better than 5Gyx3, while 1Gyx2 did not improve the NLRP3 effect." (PMID 37289257, 2023). "We found that the combination of XRT + NLPR3 agonist enhanced control of implanted lung adenocarcinoma primary as well as secondary tumors in a radiological dose-dependent manner, in which 12Gy x 3 fractions of stereotactic XRT was better than 5Gy x 3, while 1Gy x 2 did not improve the NLRP3 effect." (PMID 36824846, 2023).
thrombosis (28 papers, 2016 to 2025). "Using a murine model of venous thrombosis, the authors showed that systemic hypoxia is associated with the activation of the NLRP3 inflammatory complex and the production of IL-1β, which accelerates the development of venous thrombosis." (PMID 36014040, 2022). "In particular, it is known that neutrophils and NETosis are major inducers of venous thrombosis and hypoxia-induced venous thrombosis is linked to elevated IL-1ß and NLRP3 levels in thrombi." (PMID 34122445, 2021). "NLRP3 inflammasome activation mediates the autocatalytic activation of caspase-1, leading to maturation and secretion of IL-1β and IL-18, and has recently been implicated in the pathogenesis of thrombosis." (PMID 34977191, 2021). "This phenomenon was verified in mouse and human neutrophils, and it was found that pharmacological inhibition of NLRP3 also reduced NETosis and that NLRP3 deficiency resulted in a lower density of NETs in thrombi produced in a stenosis-induced mouse model of deep vein thrombosis." (PMID 34804066, 2021). "Finally, NLRP3 deficiency resulted in a lower density of NETs in thrombi produced by a stenosis-induced mouse model of deep vein thrombosis." (PMID 34122445, 2021). "Moreover, NLRP3-deficient mice exhibit reduced NETosis and attenuated venous thrombosis." (PMID 40520933, 2025). "NLRP3 and cleaved caspase-1 expression were significantly elevated in the atrium of MS patients with thrombus strongly indicating that for the first time, and to the best of our knowledge, that NLRP3 inflammasomes were activated and IL-1β was associated with thrombosis in MS patients." (PMID 26930272, 2016). "In the inflammatory process, the activation of the NLRP3 inflammasome and venous thrombosis involve dynamic interactions among macrophages, neutrophils, platelets, and endothelial cells." (PMID 40520933, 2025). "In thrombosis and related cardiovascular diseases, activation of the NLRP3 inflammasome is considered a key mechanism in regulating thrombosis." (PMID 40520933, 2025). "This review provides an overview of the current understanding of how the NLRP3 inflammasome promotes venous thrombosis, highlighting recent preclinical research advancements and potential therapeutic agents in this field." (PMID 40520933, 2025). "Numerous preclinical studies have shown that inhibition of the NLRP3 inflammasome and IL-1 signaling pathway can effectively prevent venous thrombosis." (PMID 40520933, 2025). "By inhibiting NLRP3, CY-09 selectively suppresses pathological arterial thrombosis while preserving physiological hemostasis." (PMID 40520933, 2025). "Investigating the impact of targeted NLRP3 inflammasome pathway inhibition on venous thrombosis development." (PMID 40520933, 2025). "Resveratrol, a polyphenol found in red wine, reduced the expression of NLRP3 and diminished the severity of venous thrombosis in a murine model." (PMID 38067137, 2023). "The NLRP3 inflammasome was recently also identified in subarachnoid hemorrhage (SAH)-dependent micro thrombosis." (PMID 38067137, 2023). "Several studies have indicated a role for the NLRP3 inflammasome in venous thrombosis, including a central role for the combined NLRP3/IL-1β activity in VTE." (PMID 37753073, 2023). "The possible role of inflammasomes in thrombosis has been outlined in a recent study showing that NLRP3 inflammasome activation and subsequent IL-1β production enhance venous thrombosis in response to hypoxia." (PMID 36674682, 2023). "Related studies have also confirmed that HIF-1α can regulate the expression of NLRP3 in a venous thrombosis model." (PMID 35449811, 2022). "In fact, genetic ablation of NLRP3 was able to curtail venous thrombosis in animals exposed to hypoxia." (PMID 34977191, 2021). "NLRP3 is expected to become a new target for the treatment of several diseases, including acute gouty arthritis, thrombosis and type II diabetes." (PMID 34804066, 2021).
thrombosis (continued). "We also observed a concomitant increase in the relative expression of NLRP3, caspase-1, interleukin-1β (IL-1β), and interleukin-18 (IL-18) transcripts in the individuals with clinically established venous thrombosis." (PMID 31653092, 2019). "It has also been reported that activation of NLRP3 inflammasome is a key determinant of venous thrombosis during hypoxic condition in venous disease." (PMID 30941060, 2019). "In summary, the NLRP3 inflammasome plays a critical role in the development of venous thrombosis, and interventions targeting it may offer new insights and strategies for the prevention and treatment of venous thrombosis." (PMID 40520933, 2025). "Additionally, NLRP3 inflammasome activation and IL-1β have been shown to promote atherogenesis and arterial thrombosis in preclinical animal models." (PMID 38267838, 2024). "Studies show that PAD4 supports NLRP3 inflammasome assembly, activating the canonical NLRP3 inflammasome pathway, leading to caspase-1 activation, inducing neutrophil NETosis, a regulated form of neutrophil cell death characterized by the release of NETs, and promoting venous thrombosis in mice." (PMID 40520933, 2025). "We next sought to verify that NLRP3 also regulates NETosis in deep vein thrombosis (DVT) to unravel the physiological importance of our findings." (PMID 34122445, 2021). "In addition, NLRP3 potentiates venous thrombosis in response to hypoxia upon IL-1β production." (PMID 31552036, 2019). "Thus it is not surprising that we observed that NLRP3 deficiency also diminished venous thrombosis." (PMID 34122445, 2021). "Our study showed a direct association between nucleotide-binding domain, leucine-rich-containing family, pyrin domain containing 3 (NLRP3) inflammasome complex and hypoxia-inducible factor 1-alpha (HIF-1α) in hypoxia-induced thrombosis." (PMID 31653092, 2019). "Hyperactivity of NLRP3 in platelets also did not modify either thrombosis prevalence or thrombus size in the model of venous thrombosis induced by partial blood flow restriction in the IVC." (PMID 37622117, 2023). "Furthermore, in deep venous thrombosis rats, TRX expression was suppressed while TXNIP and NLRP3 were elevated, wherein siTXNIP or MCC950 injection rescued the injury of a vein induced by deep venous thrombosis by improving the physiological changes and reducing the inflammatory reaction." (PMID 40643515, 2025).
cholestasis (27 papers, 2016 to 2025). Impairment of the bile flow caused by obstruction within the liver, or outside the liver in the bile duct system. "CDCA has been reported to engage the NLRP3 inflammasome, causing liver inflammation during cholestasis." (PMID 39137024, 2024). "Furthermore, Sestrin2 deficiency promoted cholestasis-induced hepatic pyroptosis by activating NLRP3 inflammasomes." (PMID 35260799, 2022). "On the other hand, during persistent cholestatic liver damage, the NLRP3 inflammasome is engaged in the process of cholestasis-induced liver injury and fibrogenesis." (PMID 36969233, 2023). "During cholestasis, the activation of the Nlrp3 inflammasome in macrophages plays a key role in contributing to disease progression." (PMID 34952202, 2022). "Our data uncovers the important role of bile acids as inflammagens during cholestasis, which activate NLRP3 inflammasome and thereby contribute to liver damage and early fibrosis in a cell type-specific manner." (PMID 34685598, 2021). "Taken together, these observations showed that PF ameliorated ANIT-induced cholestasis by restraining NF-κB/NLRP3 inflammasome pathway." (PMID 34512782, 2021). "The NOD-like receptor protein 3 (NLRP3) inflammasome pathway has been demonstrated to play an important role in liver injury and fibrosis induced by cholestasis." (PMID 32296329, 2020). "In the setting of cholestasis, increased levels of bile acids activated both the primary and secondary signals for NLRP3 activation via inducing a prominent calcium influx in macrophages." (PMID 32192118, 2020). "A previous study demonstrated that the NLRP3 pathway plays an important role in the development of liver injury and damage in cholestasis." (PMID 32296329, 2020). "Liver damage and fibrosis due to cholestasis can be alleviated by using NLRP3 inhibitors or by NLRP3 knockout in vivo." (PMID 32296329, 2020). "In case of intahepatic cholestasis the activation was through NLRP3 whereas in case of extrahepatic cholestasis the activation was through AIM2." (PMID 32985571, 2020). "Mdr2-related cholestasis could induce dysregulation of the intestinal microbiota, and toxic bile acids enter the portal vein to activate the NLRP3 inflammasome and aggravate liver injury." (PMID 36969233, 2023). "NLRP3 regulates the bile duct obstruction in experimental BA." (PMID 37255715, 2023). "In addition, our study demonstrates that Sestrin2 regulates cholestasis-induced NLRP3 inflammasome activation and pyroptosis." (PMID 35260799, 2022). "We aimed to test our hypothesis that in cholestasis bile acids act as cell-specific inflammagens by activation of the NLRP3 inflammasome in HSC and KC." (PMID 34685598, 2021). "Meantime we found that calcipotriol supplement could work to inhibit NLRP3 inflammasome activation in cholestasis through counteracting the extreme downregulation of YAP1 to alleviate live injury and fibrosis." (PMID 32296329, 2020). "Previous studies have shown that Galectin-3, a lectin produced by macrophages, may activate the NLRP3 inflammasome in the liver and contribute to collagen deposition in a murine model of cholestasis." (PMID 32192118, 2020). "Calcipotriol may work to counteract metabolic inflammation via activating VDR and overexpession of YAP1 to suppress the excessive activation of NLRP3 inflammasome in cholestasis." (PMID 32296329, 2020). "In conclusion, excessive CDCA may represent an endogenous danger signal to activate NLRP3 inflammasome and initiate liver inflammation during cholestasis." (PMID 27924062, 2016). "In addition, an increased level of bile acid could contribute to a vicious cycle of cholestasis aggravated by NLRP3 inflammasome activation." (PMID 39459978, 2024). "In this study, based on an assessment of the protective effect of PF on cholestatic liver injury, the effect of PF on SIRT1/FXR and NF-κB/NLRP3 inflammasome signaling pathway was further investigated, which might provide a deeper comprehension of PF for cholestasis." (PMID 34512782, 2021).